SLC3A2 (solute carrier family 3 member 2)
Diseases named in the same sentence as SLC3A2 in open-access papers (continued):
Sharing a sentence is not in itself a finding about the gene and the disease.
cancer (continued). "In addition, fusions of the NRG1 gene with various partner genes, such as the CD74 molecule, solute carrier family 3 member 2, and unc-5 netrin receptor D, have been identified in a wide range of cancer types, although their frequency is low with only 82 such examples out of 44,570 tumors (0.2%)." (PMID 34068503, 2021). "SLC3A2 has been reported amplify adhesive signals induced by a variety of extracellular matrix components through interactions with integrins and blocking SLC3A2 can impair a broad spectrum of adhesive signals and disrupt interactions of cancer cells with their microenvironment." (PMID 29179459, 2017). "More importantly, several cell adhesion proteins, such as BSG, ITGA2, CD9, SLC3A2 or CD151, were significantly enriched in TuNEPs and shared across cancer types." (PMID 40751052, 2025). "Due to these functions, the overexpression of SLC3A2 and SLC7A11 is related to the occurrence and development of various types of cancer." (PMID 40136510, 2025). "Forming a heterodimeric complex with 4F2 heavy chain (SLC3A2), LAT1 is highly expressed in metabolically active tissues, such as the brain, placenta, testes, and various cancers, supporting protein synthesis, cell proliferation, and metabolic function." (PMID 40574019, 2025). "The results showed that Ferroptosis-related genes such as SLC3A2, HSF1, and SLC7A11 were significantly positively correlated with SPC25 in pan-cancer." (PMID 38605119, 2024). "In the current study, we thoroughly examined the mRNA levels of NCKAP1, SLC7A11, WASF2, RAC1, SLC3A2, and RPN1 as well as the relationships between the mRNA levels of these six genes in pan-cancer." (PMID 38968580, 2024). "The results revealed that SLC7A11, SLC3A2, RPN1, LRPPRC, and GYS1 were highly expressed in several cancer tissues." (PMID 38271056, 2024). "To investigate the role of four disulfidptosis-related genes (SLC7A11, SLC3A2, RPN1, and NCKAP1) in cancer progression, we divided TCGA patients into high and low expression groups based on the median expression levels of these four genes." (PMID 38166898, 2024). "EMT properties and cancer metastasis can be suppressed by downregulating YAP/TAZ, and LYRIC, the positive regulator of EMT, can prevent cancer metastasis by inhibiting the expression of GPX4 and SLC3A2 to promote ferroptosis." (PMID 38130953, 2023). "We show here that selenium/selenocysteine can be obtained by cancer cells via multiple routes: First by the SELENOP/LRP8 axis and second, via the activity of system Xc− (SLC7A11/SLC3A2)." (PMID 37435859, 2023). "In tumor microenvironment, the released IFNγ from CD8(+) T cells suppresses SLC3A2 and SLC7A11 expression on cancer cells, consequently facilitates cancer cell accumulation of lipid peroxidation and ferroptosis." (PMID 36289191, 2022). "However, it is unclear whether iron death plays a role in the cancer-promoting effects of SLC3A2." (PMID 35057861, 2022). "Cystine/glutamate exchanger (xCT) is an important molecule mediating ferroptosis resistance in cancer cells, which is comprised of SLC7A11 and SLC3A2." (PMID 35992269, 2022). "SLC3A2, the heavy chain of the CD98 protein, is highly expressed in many cancers, including lung cancer." (PMID 36358610, 2022). "Sometimes, these ncRNAs can directly target GPX4, SLC3A2 and SLC7A11 to induce ferroptosis in cancer cells." (PMID 35342359, 2022). "Immune-active T cells are thus shielded well to secret reactive IFN-γ cytokine, reducing cancer cellular SLC7A11 and SLC3A2, cystine/glutamate transporters." (PMID 34593794, 2021). "It is noteworthy that the ferroptosis suppressor genes, SLC3A2, FANCD2, CISD1, and ACSL3, were upregulated in most cancer types, indicating that ferroptosis was generally inhibited in cancers." (PMID 34434214, 2021). "In this study, we systematically analyzed the gene expression, epigenetic regulation, and genomic alterations of six key GLNM regulators (including SLC1A5, SLC7A5, SLC3A2, SLC7A11, GLS, and GLS2) across 33 different cancer types." (PMID 34573287, 2021).
cancer (continued). "CD8+ T cells secrete interferon gamma, regulate SLC3A2 and SLC7A11 expression, and promote cancer cell lipid peroxidation and ferroptosis." (PMID 34804371, 2021). "Treating tumors with the combination of HGF and anti-IFN-γ agents restored the expression of SLC3A2 and SLC7A11, which suggested that the positive role of IFN-γ in cancer cellular ferroptosis." (PMID 34593794, 2021). "Taken together, these data revealed that an oxidative stress management network (SLC3A2, SLC7A5, and IGFBP3) under the control of p19-VHL performs an oncogenic role by overriding apoptosis in cancer stem cells." (PMID 28580172, 2017). "The cancer stem cell marker SLC3A2 was also higher among smokers in HPV+ tumors, but not statistically significant (p = 0.16), and was also higher in HPV-negative than HPV+ (p = 0.06)." (PMID 40859705, 2025). "SLC1A5, SLC3A2, and SLC7A5 are upregulated in various cancer types, which underpins the increased demand for bulk protein synthesis owing to the enhanced proliferation of cancer cells." (PMID 39757767, 2025). "In short, our investigation showed that SLC3A2 could be a novel prognostic biomarker for patients with NPC and HNSC, emphasizing its significant role in the progression of these cancers." (PMID 39926285, 2025). "SLC3A2 and SLC7A5 have been found to be highly expressed in various types of tumors or cancer cells, and they have been shown to exert pro-cancer effects in a variety of cancers through multiple pathways." (PMID 38267663, 2024). "Although the exact implication of disulfidptosis activity on cancer patients’ immune characteristics is still unknown, two disulfidptosis-related gene SLC7A11 and SLC3A2, has been reported to play a role in the immune process during tumorigenesis." (PMID 37587262, 2023). "Moreover, treatment with Dasatinib and PF573228 abrogated the transcriptional activation of SLC7A5/SLC3A2 and SSP enzymes induced by AA restriction and enhanced the inhibitory effect of low AA on cancer cell proliferation." (PMID 37880212, 2023). "Notably, NDUFA11, OXSM, LRPPRC, NCKAP1, RPN1, SLC3A2, and SLC7A11 were upregulated in cancer tissues, while NDUFS1 showed the opposite trend." (PMID 38213838, 2023). "Since SLC1A5, SLC3A2, and SLC7A5 are important for the metabolism, growth, and proliferation of cancer cells, these transporters have been targeted pharmacologically to block cancer cell growth and survival." (PMID 33953707, 2021). "Interestingly, there were 6 cancer tissues out of 14 that expressed significant levels of both SLC7A11 and SLC3A2, which we designated xCT positive tissue, while none of the normal breast tissues was xCT positive." (PMID 33672555, 2021). "Also, this shows that treatment of cancers with a SLC7A5 inhibitor or a combination of SLC7A5 and SLC3A2 inhibitors would be more effective than treatment with SLC3A2 inhibitor alone." (PMID 33953707, 2021). "Studies have confirmed that IFNG released by cytotoxic T cells downregulates the expression of glutamate transport systems (SLC3A2 and XCT), thereby promoting lipid peroxidation and iron drop in cancer cells, which explains the close relationship between immunity and ferroptosis." (PMID 34868262, 2021). "Our study demonstrated that in most cancer types, SLC1A5, SLC7A5, SLC7A11, and SLC3A2 were highly expressed and indicative of poorer survival outcomes, while the effects of changes in the expression of GLS2 and GLS depended on the type of cancer under consideration." (PMID 34573287, 2021). "Notably, SLC3A2 is significantly overexpressed in both DIPG and HGG compared with other brain and pediatric cancers." (PMID 33579942, 2021). "Similarly, the expression of SLC3A2, TUBA1B, TUBA1C, TUBB, FSTL1, and INSIG1 was affected by FIRΔexon2, suggesting that FIR and FIRΔexon2 engage in the transcription of various cancer-related mRNAs." (PMID 38139171, 2023).
cancer (continued). "Nonetheless, a comprehensive analysis of the role of SLC3A2 in cancers based on human genetic resources was still lacking, which may hinder further in-depth translational research." (PMID 35992269, 2022). "cytotoxic-T-cell-driven immunity promotes ferroptotic cell death in cancer cells, which is observed in T cell-driven antitumor immune response launched by immunotherapy with ICIs, mechanistically because of IFN-γ launching the JAK-STAT1 pathway and reducing SLC3A2, SLC7A11." (PMID 35432535, 2022). "We have shown that cancer cells that overexpress both SLC7A11 and SLC3A2 are the ones that should be considered xCT-positive, and that this pathway, through the selenocysteine biosynthesis pathway mediated production of GPX4, impacts a cancer cell’s sensitivity to various ferroptotic inducers." (PMID 33672555, 2021). "The SMC population displayed downregulation of the overall cancer cell metabolic signature (ccmGDB) and shared gene expression features of nutrient-starved cells, including upregulation of the fatty acid transporter CD36 and the amino acid transporter solute carrier family 3 member 2 (SLC3A2)." (PMID 34830962, 2021). "However, IFNγ produced by effector CD8+ T cells downregulates SLC7A11 and SLC3A2 by reducing the release of cysteine and GSH from CAFs, thereby inhibiting cystine uptake in cancer cells, resulting in the induction of tumor lipid peroxidation and ferroptotic cell death." (PMID 34796174, 2021). "These upregulated target genes are enriched for the pathways involved in metabolism (e.g., SLC3A2, SLC7A5) and mitochondrial gene expression (e.g., PNPT1), consistent with previous studies, demonstrating that elevated MYC/MYCN induces metabolic reprogramming in cancer cells." (PMID 32060267, 2020). "Cancer cell proliferation was affected by overexpression of SLC3A2-NRG1 in the HEK 293T cells, but not by expression of SLC3A2-NRG1Δ EGF." (PMID 27626312, 2016).
infection (12 papers, 2010 to 2023). The state of being infected such as from the introduction of a foreign agent such as serum, vaccine, antigenic substance or organism. "On the other hand, the supplementation with arg+/spm+ or spm+ showed lower levels of Slc3a2 compared to arg+/spd+ at 4h of infection." (PMID 37000792, 2023). "In macrophage infections, the supplementation with arg+/spd+ increased the levels of polyamines transporter Slc3a2 levels compared to MO-La/arg+ or arg+/put+ at 4h of infection." (PMID 37000792, 2023). "Viral infectivity determined by both viral RNA and protein levels in the second infection was markedly decreased by knockdown of SLC3A2." (PMID 30341327, 2018). "Indeed, we observed that after putrescine, spermidine, or spermine supplementation, the levels of Cat1, Cat2, Slc3a2, and Slc7a5 suffered some alterations, suggesting that infection and polyamines can influence transporter genes’ transcription." (PMID 37000792, 2023). "SLC3A2 also showed differential expression after infection with HIV." (PMID 31842941, 2019).
bacterial infection (1 paper, 2025). "In summary, our data suggest that the System xc- (SLC7A11 and SLC3A2) is exacerbated by the presence of F. nucleatum, promoting more L-Glutamate efflux and bacterial infection." (PMID 39743544, 2025).
metabolic disease (1 paper, 2024). A congenital disorder (due to inherited enzyme abnormality) or acquired (due to failure of a metabolically important organ) disorder resulting from an abnormal metabolic process. "Given that SLC3A2 is a member of the solute carrier family, it has been implicated in tumorigenesis, metabolic diseases, and inflammatory responses." (PMID 39769269, 2024).
SLC3A2 also shares sentences with these, for which no sentence is quoted: lymphoma (7 papers); Burkitt lymphoma (6); autoimmune disease (5); renal cell carcinoma (5); chronic lymphocytic leukemia (4); triple-negative breast carcinoma (4); B cell lymphoma (3); inflammatory bowel disease (3); lung squamous cell carcinoma (3); pancreatic ductal adenocarcinoma (3); preeclampsia (3); skin cancer (3); systemic lupus erythematosus (3); Autoimmunity (2); biliary tract cancer (2); follicular lymphoma (2); hematological cancer (2); immune disorders (2); kidney damage (2); metastatic prostate carcinoma (2); mucosa-associated lymphoid tissue lymphoma (2); myositis (2); ovarian tumor (2); type 1 diabetes (2); viral infection (2); abortion (1); acute lymphoblastic leukemia (1); adenocarcinoma (1); adrenocortical cancer (1); ankylosing spondylitis (1).
A further 61 diseases each share a sentence with SLC3A2 in 1 paper.